PON1 (paraoxonase 1)
Diseases named in the same sentence as PON1 in open-access papers (continued):
Sharing a sentence is not in itself a finding about the gene and the disease.
myocardial infarction (41 papers, 2010 to 2025). Gross necrosis of the myocardium, as a result of interruption of the blood supply to the area, as in coronary thrombosis. "The AA genotype of the rs854560 SNPs of the PON1 gene is associated with increased mortality in patients after myocardial infarction in the subpopulation of patients with lowered eGFR." (PMID 25155309, 2016). "Variations in Apolipoprotein E (APOE) and Paroxonase 1 (PON1) have been associated with Myocardial Infarction (MI) in several populations." (PMID 36980959, 2023). "It is inconceivable that PON1 has evolved to combat death from acute myocardial infarction, a syndrome unreported before the twentieth century." (PMID 38887979, 2024). "It is also important to note that the lowest reduction in plasma PON-1 concentrations occurred in patients suffering from IHD as well as myocardial infarction." (PMID 39114750, 2024). "A few studies demonstrate that serum PON1 activity decreases in patients with acute myocardial infarction." (PMID 28376720, 2017). "1999: Serum PON1 activity low within 2 h of acute myocardial infarction." (PMID 38887979, 2024). "A recent study on patients with non-ST-segment elevation myocardial infarction showed that diminished PON1 levels were found in those who had an increased risk of death." (PMID 38474211, 2024). "Also, it is believed that PON1 activity is already diminished before the acute event, since the activity is lower within 2 h of the symptoms of myocardial infarction." (PMID 38474211, 2024). "Low serum PON-1 activity is significantly reduced in patients with myocardial infarction (MI), which may be the reason for the development of CAD." (PMID 39336967, 2024). "1986: Serum PON1 activity decreased in myocardial infarction survivors." (PMID 38887979, 2024). "After the initial case-control study showing an association between PON1 activity and myocardial infarction, we performed another study in which it was found that serum PON1 activity was already low in samples taken within 2 h of the onset of symptoms of acute myocardial infarction." (PMID 36873390, 2023). "The aim of this study was to evaluate the high-density lipoprotein structure and functionality, by measuring biomarkers of the structure (i.e., free and esterified cholesterol), diameter by particle size, and functionality (i.e., PON-1 activity) in the occurrence of acute myocardial infarction." (PMID 30944734, 2019). "Observed in this study dynamic changes of PON1 activity may be compared to PON1 activity changes during myocardial infarct." (PMID 28376720, 2017). "We also did not replicate associations between PON1 polymorphisms and either myocardial infarction or lipid profile." (PMID 25155309, 2016). "We found that PON1-RR smokers presented a clinically highly relevant increase of 9.4 points on the Framingham risk index as compared to non-smoking PON1-QQ/QR individuals and thus almost a 10% higher risk for having a myocardial infarction in 10 years." (PMID 27812605, 2016). "We analysed PON1 55 polymorphism in a total of 440 elderly patients who underwent an ACS episode: 98 patients affected by unstable angina (UA), 207 AMI (acute myocardial infarction) patients affected by STEMI (ST elevation), and 135 AMI patients affected by NSTEMI (no ST elevation)." (PMID 22536511, 2012). "A similar trend was observed in the non-conventional lipid-related ASCVD biomarkers (PON-1 and LCAT), where myocardial infarction and IHD patients were noted to have the lowest concentrations of plasma PON-1 and LCAT." (PMID 39114750, 2024). "The lowest mean plasma PON-1 concentration was noted in IHD patients, followed by patients suffering from myocardial infarction." (PMID 39114750, 2024). "The present study demonstrated significant decreases in plasma PON-1 and LCAT levels with severe alterations in atherogenic lipids and lipoproteins in ASCVD patients, especially the subtypes of myocardial infarction and IHD." (PMID 39114750, 2024).
myocardial infarction (continued). "Overall, this pilot study demonstrated that consuming HP-EVOO may have beneficial effects on the antioxidant status of patients with a history of myocardial infarction, such as FRAP and PON-1 activity." (PMID 40722971, 2025). "Thus, it suggests the crucial role PON-1 plays in the presentation of IHD and myocardial infarction." (PMID 39114750, 2024). "PON1 is an antioxidant enzyme that prevents the peroxidation of LDL and in myocardial infarct patients, a negative association was observed between PON1 concentrations and malonyl aldehyde (MDA) concentrations, an oxidative stress marker." (PMID 30975138, 2019). "In all cases of myocardial infarction, median serum levels of APO-A1, ox-LDL and PLA2 were 120.36 mg/dl, 23.72 ng/ml and 4.1 ng/ml, respectively, whereas the mean serum Apo-B, anti-oxidized LDL antibody and PON-1 levels were 83.48 ± 27.98 mg/dl, 14.6 ± 1.8 ng/ml and 3.12 ± 1.07 ng/ml respectively." (PMID 39351476, 2024).
Alzheimer disease (40 papers, 2010 to 2025). A progressive, neurodegenerative disease characterized by loss of function and death of nerve cells in several areas of the brain leading to loss of cognitive function such as memory and language. "Low PON1 activity has been linked to a potential risk factor for neurological disorders, including Alzheimer’s disease." (PMID 41590633, 2025). "The association between the A allele of the rs705379 PON1 polymorphism with Alzheimer’s disease in a Caucasian population was observed." (PMID 39684839, 2024). "Although these changes are linked to CVD, Alzheimer’s disease, and cancer, the molecular mechanisms by which PON1 affects gene expression remain to be elucidated in future studies." (PMID 39594433, 2024). "For instance, Alzheimer’s disease is associated with a damage of oligodendrocytes from one side, and compensatory intensified transport of PON-1 to oligodendrocytes to reduce the oxidative imbalance from another side." (PMID 37511134, 2023). "PON1 has also been implicated in Alzheimer’s disease (AD), which can be expected given that AD has a significant vascular component." (PMID 36899882, 2023). "Paraoxonase 1 (PON1), a homocysteine (Hcy)-thiolactone detoxifying enzyme, has been associated with Alzheimer’s disease (AD), suggesting that PON1 plays an important protective role in the brain." (PMID 36899882, 2023). "In patients with Alzheimer’s disease, the homozygous TT genotype (PON1 C-107T) was associated with a change in the distribution of lipoprotein cholesterol with a higher prevalence of a smaller and denser LDL." (PMID 33374313, 2020). "Here we review the studies, in humans, of the association between PON1 and four neurodegenerative diseases: Multiple sclerosis, amyotrophic lateral sclerosis, Alzheimer’s disease and Parkinson’s disease." (PMID 33374313, 2020). "The PON1-L55M and PON1-Q192R genotypes, the two most important coding region polymorphisms of PON1, are related to the occurrence of Parkinson’s disease, Alzheimer’s disease, and amyotrophic lateral sclerosis." (PMID 33013750, 2020). "PON1 has also been implicated in Alzheimer’s disease (AD), which is expected given that AD has a significant vascular component." (PMID 33260536, 2020). "The aim of this study was to determine the distribution of PON1 polymorphism in patients with Alzheimer’s disease in Gorgan and compare it with a healthy control group." (PMID 28694880, 2017). "In the brain, PON1 polymorphisms rs662 and rs854560 is involved in Alzheimer’s disease neuropathology." (PMID 28962559, 2017). "PON1 has been implicated in the etiology of a number of adult-onset neurologic diseases such as Parkinson and Alzheimer diseases." (PMID 21126941, 2010). "PON1 polymorphisms and/or enzyme measurements have been associated with various diseases of the nervous system, including Alzheimer’s disease, brain tumors, vascular dementia, amyotrophic lateral sclerosis, ischemic stroke, and Parkinson disease." (PMID 21126941, 2010). "Reduced PON1 activity is associated with increased oxidative stress and elevated levels of lipid peroxidation products, both of which are key contributors to the pathogenesis of late-onset Alzheimer’s disease and vascular dementia." (PMID 41303537, 2025). "Impaired PON-1 activity has also been reported to be associated with a higher prevalence of atherosclerotic cardiovascular disease in patients with rheumatoid arthritis and Alzheimer’s disease." (PMID 35313365, 2023). "Onset of Alzheimer’s disease may depend on different polymorphisms of the PON1 enzyme." (PMID 28694880, 2017). "A role for PON1 has also been identified in neurological disorders, particularly in Alzheimer’s disease and Parkinson’s disease (PD)." (PMID 41303537, 2025). "PON1-dependent metabolic changes can lead to atherothrombotic cardiovascular disease, Alzheimer’s disease, and cancer." (PMID 39594433, 2024).
Alzheimer disease (continued). "Paraoxonase-1 (PON1), a serum antioxidant enzyme, has been implicated in Alzheimer’s disease (AD) pathogenesis that involves early oxidative damage." (PMID 38672443, 2024). "We were among the first to demonstrate a significant reduction in serum PON1 activity in patients with Alzheimer’s disease (AD) and Vascular Dementia, the most common forms of dementia." (PMID 39456469, 2024). "Serum PON1 activity has been negatively correlated with urinary 8-OHdG levels in patients with Alzheimer’s disease and laryngeal squamous cell carcinoma." (PMID 25741997, 2015). "In line with this, deficiencies in Hcy‐thiolactone–detoxifying enzymes, including paraoxonase 1 (PON1) and bleomycin hydrolase (BLMH), have been linked to Alzheimer's disease pathology, suggesting that inadequate clearance of Hcy‐thiolactone contributes to neurodegenerative risk." (PMID 41427720, 2025). "PON1 has been extensively studied in relation to Alzheimer’s Disease (AD), but the role of PON3 remains unknown." (PMID 39456469, 2024). "PON1 enzymatic activity has also been investigated in the context of Alzheimer’s dementia and vascular dementia, where it has been demonstrated that paraoxonase activity and arylesterase activity are both reduced in dementia patients compared to healthy controls." (PMID 36829958, 2023). "Interestingly, in patients with dementia such as Alzheimer's disease (AD), the activity of PON1 decreases, suggesting that PON1 may play a neuroprotective effect." (PMID 33628379, 2021). "In T1DM, some of the terms annotated were related to myelin dysregulation (ARHGEF6, CNP, NADK2, PSAP, SLC25A12) and other neurological disorders, such as Alzheimer’s disease (i.e., POA2, APOC1, APOC3, CNP, GSK3B, PON1, PSAP, SELENBP1) or movement disorders." (PMID 39901093, 2025). "PON1 has been studied in the fields of toxicology, CVD, renal disease, liver disease, Alzheimer’s disease, and cancer." (PMID 39594433, 2024). "In conclusion, our study is the first to explore serum PON3 in the context of Alzheimer’s disease (AD) and mild cognitive impairment (MCI) and to compare its pattern with PON1-arylesterase activity." (PMID 39456469, 2024). "The pleiotropic role of PON1 might account for the documented association between low circulating levels of its activities and the risk for cardiovascular disease (CVD), but also pathologies affecting the brain, such as vascular dementia (VaD) and late-onset Alzheimer’s diseases (LOADs)." (PMID 32466344, 2020). "Reduced PON1 activity accompanied by increased oxidative stress and inflammation is a common finding in patients with CVD, diseases of the kidney and liver, Alzheimer’s disease, and cancer." (PMID 39594433, 2024). "This study showed the localization of PON-1 and PON-3 around and inside Aβ plaques in a murine model of Alzheimer’s disease (AD), suggesting that HDL particles carry PON-1 and PON-3 from the liver, where they are synthesized to areas of high levels of inflammation and oxidative stress." (PMID 37108044, 2023). "Unlike in our results, CSF PON1 activity was reported to decrease with the progression of neurodegenerative diseases and Alzheimer’s disease, as well as dementia." (PMID 34769107, 2021). "Despite the potential significance of PON3 in Alzheimer’s disease pathology and its functional similarities to the extensively studied PON1, no human studies have investigated whether changes in peripheral PON3 levels are associated with the disease." (PMID 39456469, 2024).
Hypertension (39 papers, 2012 to 2026). The presence of chronic increased pressure in the systemic arterial system. "PON1 Q192R genotype frequencies: QQ 38%, QR 44%, RR 18%; association of the 192Q allele with increased hypertension risk and overall cardiovascular risk." (PMID 40428368, 2025). "In Colombian populations, the PON1 Q192R polymorphism has been linked to both decreased susceptibility to coronary artery disease and increased risk of hypertension, with the distribution of the alleles varying between regions." (PMID 40428368, 2025). "Their findings indicated significant gene–environment interactions, where the PON1 Q192R variant was linked with hypertension and cardiovascular risk, possibly mediated by occupational pesticide exposure." (PMID 40428368, 2025). "Specifically, after adjusting for age and hypertension, the PON1 192 R allele (QR + RR) was found to be associated with a statistically significantly higher risk of RVO compared to the QQ genotype (OR = 2.51; 95% CI = 1.02-6.14, p = 0.04)." (PMID 38927649, 2024). "Recent data suggest an association between PON1 and arterial hypertension with PON1 concentration being significantly lower in hypertensive patients." (PMID 29333213, 2017). "Using a regression model, we determined that hypertension, male gender, higher plasma fibrinogen levels, and the lower frequency PON1 55 LL genotypes were positive risk factors for RVO." (PMID 23441121, 2013). "We also found a significant association between PON-1 and hypertension in CAD cases." (PMID 39336967, 2024). "On the other hand, coffee harvesters carrying the PON1 Q192R variant showed decreased PON1 activity, affecting the hydrolysis of pesticides and oxidized lipids, which caused increased intoxication and higher cardiovascular risk, associated with hypertension." (PMID 35326157, 2022). "However, our study shows the importance of additional risk factors, including hypertension, and valuable markers such as PON-1 and SRB-1 levels, which may be useful for predicting CAD in the Indian population." (PMID 39336967, 2024). "Although most data indicate, as previously stated, that PON1 cooperates in the control of hypertension by means of increased eNOS activity, there is evidence that, via an unrelated mechanism, PON1 can promote high blood pressure." (PMID 31817387, 2019). "Additionally, we searched for potential interactions between PON1 alleles and common traditional risk factors of CAD including cigarette smoking, hypertension, and plasma lipid abnormalities." (PMID 29118461, 2017). "This novel correlation unveils a previouslyunrecognized connection between hypertension andoxidative stress in the context of pediatric NS.Additionally, there is a noticeable reduction in antioxidantcapacity during the acute phase, as demonstratedby diminished levels of -SH, PON 1, and TAS." (PMID 39139165, 2024). "The PON-1 level was significantly different, and higher, in cases that were presented with hypertension, compared to cases with no hypertension (p = 0.002)." (PMID 39336967, 2024). "Among these factors, age, alcohol consumption, hypertension, and lipid drugs did not affect serum PON1 activity." (PMID 28038449, 2017). "The distribution of the baseline characteristics was not different within the various PON1 genotypes with respect to age, sex, adiposity, lipid profile prevalence of hypertension, and insulin resistance." (PMID 25477710, 2014). "The objective of this study is to examine theparameters of oxidative stress status (TOS, AOPP,PAB, -SH, PON 1 and TAS), inflammatory biomarkers(PTX 3, leptin, PDL-1 and e-cadherin) in pediatricpatients with NS during the acute phases of NS in relation to their hypertension status." (PMID 39139165, 2024). "Indeed, we found that PON1 was decreased in women and, to a lesser extent, in men, but only in women was the difference independent of confounders such as age, smoking status, hypertension, and HDL-c." (PMID 32751395, 2020).